CCL7 (C-C motif chemokine ligand 7)
Diseases named in the same sentence as CCL7 in open-access papers (continued):
Sharing a sentence is not in itself a finding about the gene and the disease.
tumor (continued). "Of these tumor size-associated cytokines, seven (TNF-β, MCP-3/CCL7, Fractalkine/CX3CL1, GRO/CXCL1, sCD40L, TGF-α, and MDC/ADAM11) were among those newly investigated as part of a bead array-based vitreous cytokine analysis of UM." (PMID 37509362, 2023). "In a previous study that examined MCP-3/CCL7 in the aqueous humor of UM-containing eyes, the level of this cytokine showed correlation with the density of tumor-infiltrating CD68+ macrophages." (PMID 37509362, 2023). "Of note, CCL7 has been summarized to play critical prooncogenic role in cancers via a multitude of mechanisms, including the recruitment of immune cells to the tumor sites." (PMID 36118415, 2022). "Collectively, this research suggests that LINC01094 binds to SPI1 to promote its nuclear translocation, which further activates CCL7 transcription by binding to its promoter, leading to M2 macrophage accumulation and dissemination of tumor cells." (PMID 36118415, 2022). "CCL7 exerts its carcinogenesic properties as a chemoattractant for neutrophils involved in the formation of the tumor microenvironment." (PMID 35784290, 2022). "CCL7 can be expressed in cell types such as immune cells, stromal cells, and airway epithelial cells and can also be expressed in various tumor cells under pathological conditions." (PMID 35281057, 2022). "In the present study, we observed that CCL7, which can be upregulated by LINC01094-mediated SPI1, is linked to increased tumor M2 macrophage accumulation and malignant development of LUAD cells." (PMID 36118415, 2022). "The DEN/CCl4-treated Cxcl10−/− mice, in turn, displayed a significant enhancement of chemokines in tumor tissue in comparison to the surrounding tissue (Ccl5, Ccl2 and Ccl7)." (PMID 35897689, 2022). "The tumor-infiltrating lymphocytes most closely related with CEMIP expression in BC were CCL7, CCL14, CCL20, and CXCL14." (PMID 35370456, 2022). "CCL7 was shown to recruit monocytes to promote tumor cell invasion, migration and infiltration by stimulating tumor angiogenesis." (PMID 35454769, 2022). "In this work, the promoting roles of CCL7 in M2 skewing and tumor development were validated in vivo that the CCL7 suppression blocked the xenograft tumorigenic ability of cells and suppressed M2 macrophage infiltration in the tumor tissues." (PMID 36118415, 2022). "CCL7 (Chemokine C-C Motif Ligand 7) plays an important role in the recruitment of monocytes, calcium influx, tumor metastasis, and other biological effects." (PMID 36193415, 2022). "Some studies indicate that CCL7 can promote tumor invasion and metastasis; however, other studies suggest that CCL7 has tumor suppressor effects." (PMID 36109744, 2022). "CCL2, CCL3, CCL5, and CCL7 attract monocytes/macrophages to exert anti-infective, anti-tumor, and immunomodulatory effects at sites of inflammation." (PMID 36188003, 2022). "The chemokines CCL2, CCL7, and CCL8 are expressed in many cancer types as well as cancer-associated fibroblasts (CAFs), tumor-associated macrophages (TAMs), MDSCs, and mesenchymal stem cells found in the TME, which support the tumor growth and metastasis." (PMID 35432319, 2022). "Macrophages are attracted to tumor sites expressing chemotactic factors such as CCL7, CCL8 and CXCL12." (PMID 34001208, 2021). "Accordingly, transfection with CCL7/MCP-3 hampered tumor growth and prevented metastasis in animal models of cancer." (PMID 34884259, 2021). "Tumor EVs induced expression in macrophages of pro-invasive markers Ccl7, Tnfr2, Mmp12, and Slpi compared to an M-CSF only control." (PMID 34298673, 2021). "The expression of CCL2 was upregulated 11.1-fold in tumor-adjacent tissue, and 5.3-fold in tumors compared to normal mucosa, in CCL7 2.3- and 1.9-fold, and in CCL8 8.3- and 2.1-fold." (PMID 34885960, 2021).
tumor (continued). "Meanwhile, decreased expression of CCL2 and CCL7 was detected in the experimental group, and the expression of CCL2 is closely associated with tumor angiogenesis and high invasiveness, while CCL7 has a recruitment effect on Treg." (PMID 35095931, 2021). "CCL7 is expressed in various cell types, e.g., stromal cells, airway smooth muscle cells, and keratinocytes, under physiological conditions, and in tumor cells under pathological conditions." (PMID 34653236, 2021). "In case of PCa, adipocytes from periprostatic AT (PPAT) secrete CC-chemokine ligand 7 (CCL7) which can diffuse through prostatic capsule to reach the tumor." (PMID 34354670, 2021). "Although some reports have shown the anti-tumor activity of CCL7, most studies support its pro-tumor effects." (PMID 34206004, 2021). "Ccl2 and Ccl7 control the recruitment of monocytes and neutrophils to the inflamed or tumor tissues, while Ccl17 attracts regulatory T cells." (PMID 34504786, 2021). "The results suggested that the mRNA levels of CCL7 were significantly higher in tumor tissues than in normal tissues, as we have observed for CCL2833." (PMID 33257678, 2020). "The highest upregulation in LECs after direct interaction with the tumor cells was observed for the cytokines CCL7 and CXCL6." (PMID 31963450, 2020). "We found commonly deregulated factors in LECs in both metastatic tumor cell models, namely a strong up-regulation of E-selectin, cytokine CCL7, and complement component 3 (C3)." (PMID 31963450, 2020). "Results from immunohistochemistry (IHC) and integrated optical density (IOD) analysis with NSCLC tissue arrays of tumor and normal lung tissues (Cohort 3) confirmed that the protein levels of CCL7 were higher in tumor tissues than in the normal lung tissues." (PMID 33257678, 2020). "Administration of CCL7 significantly prolonged the survival of KP mice and inhibited tumor development at 8 weeks after tumor induction." (PMID 33257678, 2020). "Previous studies have shown that CCL7 is secreted by various cells such as tumor cells, fibroblasts, epithelial cells and macrophages." (PMID 32874132, 2020). "Administration of CCL7 into lungs alone or in combination with anti-PD-1 significantly inhibits tumor development and prolongs the survival of KP and KL mice." (PMID 33257678, 2020). "Consistently, anti-PD-1 treatment significantly inhibited tumor development of the KP mice, which was further inhibited by combined injection of CCL7 compared to the empty vector." (PMID 33257678, 2020). "On the other hand, an increased expression of CCL2 and CCL7 has shown anti-tumor effects in cervical carcinoma, glioma and mastocytoma induced by gene therapy in laboratory animals." (PMID 33182504, 2020). "Consistently, administration of CCL7 significantly prolonged the survival of KP or KL mice and inhibited tumorigenesis in the lungs of KP or KL mice after tumor induction." (PMID 33257678, 2020). "CCL7 exhibits high expression in NSCLC tumor tissues and is positively correlated with the infiltration of cDC1 in the TME and the overall survival of NSCLC patients." (PMID 33257678, 2020). "LCM from SUM159 tumor-bearing mice contained 16 unique proteins relative to other LCM conditions, including the metastasis-associated proteins CCL7, FGFR4, GM-CSF, MMP3, thrombospondin-1 and VEGF." (PMID 31936750, 2020). "Compared with the ER+BCC-NAF organoid co-cultures, the tumor-associated CD45+CD31+ cells secrete 5.7 ± 0.48-fold more IL1β, 1.5 ± 2-fold CCL7, 1.2 ± 0.2-fold IL6, and 1.1 ± 0.02-fold IL8." (PMID 31419632, 2019). "We analyzed the effect of CCL7 overexpression on tumor progression in a murine CT26 model, where cells overexpressing CCL7 accelerated the early phase of tumor growth and caused higher lung metastasis rates compared with control mice." (PMID 30764543, 2019). "It is therefore possible that SPC25 is a downstream target of CCL7 and is partially responsible for CCL7-induced promotion of tumor cell proliferation." (PMID 31400751, 2019).
tumor (continued). "Tumor‐derived chemotactic factors such as Ccl2, Ccl3, Ccl5, and Ccl7 are known to recruit macrophages to the growing tumor." (PMID 29047229, 2018). "Stably overexpressed CCL7 in tumor cells can restrain tumor growth in multiple mouse tumor models, including models of human cervical tumor, melanoma, malignant glioblastoma, PDAC, and CRC." (PMID 29915688, 2018). "Increased CCL7 expression indicates extensive invasion, lymph node metastasis, and higher tumor-node-metastasis stage." (PMID 29915688, 2018). "In this review, we provide an overview of CCL7 in tumorigenesis, and the data presented herein are expected to provide new approaches for tumor therapy." (PMID 29915688, 2018). "In clinical specimens, higher CCL7 expression in liver metastatic tumor tissues suggested that CCL7 promotes CRC liver metastasis." (PMID 29915688, 2018). "Correspondingly, CCL7 overexpression in tumors enhances recruitment of macrophages, dendritic cells, neutrophils, and natural killer cells and slows tumor growth." (PMID 30671055, 2018). "Chemokine C-C motif ligand 7 (CCL7) produced in periprostatic WAT was found to stimulate the migration of chemokine receptor type 3-expressing tumor cells." (PMID 30567335, 2018). "CCL7 not only inhibits tumor growth but also completely blocks tumor metastasis in a mouse colon cancer CMT93 model." (PMID 29915688, 2018). "CCL7 is an important molecular regulator in the reciprocal interaction between stromal cells and tumor cells, which can not only participate in the tumorigenesis but also exert its antitumor effect in specific contexts." (PMID 29915688, 2018). "Of these, interleukin‐1β (IL‐1β) showed age‐dependent upregulation in control lungs and tumors from old mice, whereas tumor‐specific upregulation was observed for Ccl7, IL‐15ra, and Cxcr6 cytokines in old mice." (PMID 29047229, 2018). "Upon binding to its receptor CCR2, CCL7 plays a pivotal role in the recruitment of macrophages by tumor cell-derived exosome-educated MSCs." (PMID 29915688, 2018). "Increased CCL7 levels recruit monocytes to sites at the tumor periphery, which helps in the formation of an environment suitable for carcinoma progression and promotes monocytes to complete phenotypic transformation." (PMID 29915688, 2018). "Nonetheless, T lymphocytes and DCs activated by CCL7 play an important role in mobilizing the immune response to resist tumor growth, and CCL7 is expected to be an appealing antitumor molecular target under certain circumstances." (PMID 29915688, 2018). "Tumor-resident MSCs overexpressing CCL7 are liable to provide a suitable microenvironment for tumor growth by increasing the interaction with surrounding immune cells and by promoting macrophage infiltration." (PMID 29915688, 2018). "The release of IFN-γ in the tumor is a marker of a Th1 response, which is a key for the antitumor effect of CCL7 and amplifies the cytocidal activities of leukocytes by cooperating with the perforin/granzyme-mediated system." (PMID 29915688, 2018). "In this study, we investigated how CCL7 induced tumor cell metastasis using both in vitro and in vivo approaches." (PMID 27167205, 2016). "The enhancement of tumor growth in nude mice by CCL7 overexpression appeared to be much more pronounced after an initial period." (PMID 27167205, 2016). "We used in vitro and in vivo approaches (murine models) but also human tumours to show that mature adipocytes secrete CCL7, which diffuses through the capsule to the peripheral zone of the prostate." (PMID 26756352, 2016). "Based on these observations in vivo, we conclude that CCL7 has a critical role in tumor proliferation and metastasis and this role is related to CCR3." (PMID 27167205, 2016). "CCL7 is a relatively understudied cytokine, however its expression in tumor stroma has been shown to enhance invasion and migration of oral squamous carcinoma cells." (PMID 26046767, 2015).
tumor (continued). "In this study, we demonstrated the tumor suppressive role of let-7d in RCC and validated that the targets of let-7d were COL3A1, an important stroma component, and CCL7, a chemokine attracting monocytes to tumor tissue." (PMID 25193015, 2014). "Both proteins, IL-1α and -β, have been implicated in tumor progression by inducing the expression of angiogenic and metastatic genes, cytokines and growth factors, such as MMPs, VEGF, IL-6 and 8, CCl2, CCL7, TNFα and TGFβ." (PMID 24887580, 2014). "In contrast, silencing of CCL8 suppressed only the recruitment of innate immune cells, while silencing of CCL7 reduced tumor cell proliferation almost to the levels observed in tumors growing in the absence of co-injected fibroblasts." (PMID 24068959, 2013). "Of those molecules a number of have been associated with cell migration/invasion, tissue remodeling and inflammatory response, processes that are likely to influence tumor cell invasion, including MCP-3 (CCL7), osteopontin, TGFB-1, IL-6 and IL-8." (PMID 23349962, 2013). "CCL7 is produced by macrophages and by certain tumor cells, and specifically attracts monocytes and regulates macrophage function." (PMID 23935890, 2013). "To confirm the inhibition of tumor growth associated with decreased chemokine expression in Ccn1‐KO tumor, we focused on CXC chemokines, including CXCL1, CXCL3, and CXCL5, which bind to CXCR2, as well as CCL2 and CCL7, which bind to CCR2." (PMID 40287974, 2025). "Moreover, CCL7 contributes to shaping the immune components of the tumour microenvironment, which can further support tumour growth and progression." (PMID 41440554, 2025). "The authors initially identified CCL3 as a factor suppressing tumor growth in vivo; however, in contrast to CCL7, their screening approach under anti-PD-1 therapy suggests that it may also play a role in driving immune cell exclusion from the tumor site." (PMID 39837825, 2025). "Furthermore, 5'tRF-GlyGCC/LDHA axis induces macrophage infiltration and polarization toward an M2 phenotype, mediated by the chemokine CCL7, thereby reshaping the tumor microenvironment." (PMID 41309487, 2025). "Our study further confirmed that CCL7 facilitated tumor growth in vivo." (PMID 40062588, 2025). "The treatment of CCL7 increased tumor volume and tumor weight in nude mice." (PMID 40062588, 2025). "To investigate whether ZBP1 modulates CCR1 expression in tumor cells via CCL7 produced by CAFs, we employed a co-culture system." (PMID 41430036, 2025). "Inflammatory mediators such as IL1β, IL6, and MCP-3 (CCL7) not only drive SCC cell growth but also recruit and condition myeloid populations, including monocytes, tumor-associated macrophages, and MDSCs, thereby promoting a suppressive, tumor-permissive niche." (PMID 41510255, 2025). "Notably, our findings demonstrate that CCL7 expression is significantly higher in HCC tumor tissues compared to adjacent non‐tumorous tissues." (PMID 40062588, 2025). "However, during pathological processes such as inflammation and tumorigenesis, there is an upregulation in both the expression level and activity of CCL7, which further promotes inflammatory response and tumor development." (PMID 40062588, 2025). "Furthermore, IHC staining showed that the expression of CCL7 was increased in HCC tumor tissue and portal vein tumor thrombus tissue compared with paracancer tissue." (PMID 40062588, 2025). "Also, Ccl2, Ccl7, and IL-15 which have anti-tumor responses were upregulated in this cluster, which likely contributes to the IFNα-mediated antiphagocytic activity of macrophages." (PMID 39559365, 2024). "CCL7 can exert a dual role in cancer, being able to promote or suppress tumor growth." (PMID 39090759, 2024). "CCL7 binds to specific receptors, promoting the migration and aggregation of monocytes and macrophages, and plays a role in immune and inflammatory responses as well as tumor development." (PMID 39334887, 2024).
tumor (continued). "By analyzing the differentially expressed genes between the cryoablation group and the control group, we found that cryoablation of the primary tumor significantly increases the expression levels of several chemokines in the secondary tumors, including Ccl2, Ccl6, and Ccl7." (PMID 39489086, 2024). "Similarly, pharmacologic inhibition of STAT3 or genetic depletion of CCL2 and CCL7 reduced pro-tumor CD45highCD11b+CD68+CD206+ macrophages in CT2A tumors." (PMID 38443336, 2024). "In these experiments, changes in cell migration behaviour were observed, and molecules such as chemokine CCL7 (C-C Motif Chemokine Ligand 7) secreted by PPAT-adipocytes were demonstrated to stimulate the migration of tumour cells expressing CCR3 (CCL7 chemokine receptor)." (PMID 39010137, 2024). "Moreover, in patients with NSCLC, the higher expression of CCL7 in tumor tissues was positively correlated with an increased number of tumor-infiltrating DCs and better overall survival." (PMID 37046033, 2023). "Interestingly, in tumors lacking the Il1b gene, there was a significant induction of chemokine CCL7, in contrast to the in vitro data performed with tumor cell cultures." (PMID 37733448, 2023). "Therefore, CCL2 and CCL7 are the main CC chemokines secreted by the 231 TFM tumor spheroids that induce monocyte recruitment from the vasculature." (PMID 38076998, 2023). "The upregulation of CCL2 and CCL7 implies the high number of immune cells in the tumor." (PMID 37334114, 2023). "It should be noted that Ccl7 or Ccl8/12 are depleted in the TME but are retained in tumor cells." (PMID 37012245, 2023). "Interestingly, all these GEP class-associated cytokines (PDGF-AB/BB, MCP-3/CCL7, TNF-β, G-CSF, IL-13, and IL-3) were also among the tumor size-correlated cytokines." (PMID 37509362, 2023). "Then, we verified whether early OCPs in tumor microenvironment could recruit more early OCPs through a CCL7-dependent way." (PMID 35715847, 2022). "In breast cancer, CCL2 and CCL7 have been reported to promote tumor malignancy." (PMID 36347994, 2022). "CCL2 and CCL7, both highly expressed in tumor microenvironment, can recruit various immune cells (such as myeloid-derived suppressor cells, MDSCs) to form an immune-suppressive microenvironment, allowing tumor cell to evade from the body's immune surveillance and supporting tumor cell proliferation." (PMID 36347994, 2022). "Furthermore, we unexpectedly found early OCPs in tumor microenvironment were the dominant source for CCL7." (PMID 35715847, 2022). "Distinct from the naïve condition, cells from the tumor-bearing animal migrate to CCL2 with a slightly higher potency as compared to CCL7 and achieve near-maximum migration to both ligands at as low as 3ng/mL of recombinant protein plated in the bottom chamber." (PMID 36685592, 2022). "For instance, one chemokine, i.e., CCL2, might be the prominent driver of CCR2+/CX3CR1+ cell recruitment to the tumor, while the second, i.e., CCL7, is more important for homing to specific niches within tumor." (PMID 36685592, 2022). "CCR1, CCR2 and CCR3 were reported to be potential receptors of CCL7 in tumor microenvironment." (PMID 35715847, 2022). "On one hand, transfection with CCL7 has been shown to retard or completely inhibit tumor growth and prevent formation of metastasis, on the other–MCP-3 facilitates the formation of an environment favoring carcinoma progression and promotes phenotypic transformation in monocytes." (PMID 34885960, 2021). "Long-time and low-dose of CCL7 inhibitor treatment might be a promising alternative strategy to induce tumor dormancy and immune evasion, thus reduce tumor recurrence and prolong the survival of CRC patients." (PMID 33986252, 2021). "NEFM transcriptional expression was negatively associated with CCL7, CCL8 and CCL18, which would recruit monocytes to differentiate into tumor-associated macrophages (TAMs) at the tumor site, indicating that NEFM may cause decreased M2 macrophage infiltration." (PMID 34001208, 2021).